CCR4 (C-C motif chemokine receptor 4)
Diseases named in the same sentence as CCR4 in open-access papers (continued):
Sharing a sentence is not in itself a finding about the gene and the disease.
cancer (continued). "Based on the presented data, we concluded that, on the one hand, CCR4 acted as an oncogene and promoted cancer cell proliferation, migration, epithelial-mesenchymal transition (EMT) and tumorigenesis, to facilitate cancer progression in ccRCC." (PMID 34180759, 2021). "Another therapeutic approach is the use of anti-CCR4 antibodies or CCR4 antagonists (receptor for CCL17/TARC and CCL22/MDC) in cancer therapy to reduce the accumulation of Treg and thus enhance the immunotherapy and anticancer response of the immune system." (PMID 32781743, 2020). "Our results showed that the heat diffusion algorithm predicted 5 putative cancer gene CDH10, CHST11, GRM3, VAV1 and CCR4 from Tier 2 of the Cancer Gene Census6." (PMID 31500564, 2019). "High expression of CCR4 and CCR10 correlated with poor cancer‐specific survival (p < 0.045)." (PMID 40896244, 2025). "Our survival analysis revealed that high expression of CCR3, CCR4, and CCR10 is associated with poor cancer‐specific survival in FL‐patients, a finding that has not been reported previously." (PMID 40896244, 2025). "This review shows the essential roles of CNOT2 in maintaining cancer cellular homeostasis and explores its interactions within the CCR4-NOT complex that influence transcriptional and post-transcriptional regulation." (PMID 40864769, 2025). "A previous study showed that the CCR4-Not complex regulates genomic stability, making it a target of interest for cancer therapies." (PMID 39599711, 2024). "CCR4 and its ligands CCL17 and CCL22 are also involved in cancer cell migration." (PMID 39114657, 2024). "We identified a non-significant expression of CCR4 in each group; CCR4 expression was equal in the cancer group when compared to the control group, slightly higher in the metastatic group, and lower in the KRAS-positive group." (PMID 37869102, 2023). "CCR4 is bound by CCL22, which is positively coexpressed with OLFML2B in 22 cancers." (PMID 35873458, 2022). "SNX-482 was also shown to upregulate the expression of CCR4 (C-C motif chemokine receptor 4), IFNG (IFN-gamma), GZMB (granzyme B) and PDCD1 (programmed cell death protein 1) genes, which are important for anti-cancer activity." (PMID 36119523, 2022). "All current findings suggested that CCL2-CCR4-Vav2-Rac1-p-MLC signaling plays an essential role in cell migration and cancer metastasis of HNSCC, and CCR4 may serve as a new potential molecular target for HNSCC therapy." (PMID 35177591, 2022). "Actually, dysregulation of deadenylases in the Ccr4–Not complex or PARN has been observed in several types of cancers." (PMID 33671234, 2021). "CNOT2, a subunit of the CCR4-NOT complex, is known to be associated with apoptosis, angiogenesis, autophagy, and metastasis in several types of cancer cells." (PMID 34680125, 2021). "Chronic hypoxia also enhances the effect of the described chemokines on cervical and ovarian cancer cells by increasing the expression of the CCR4, CCL17/TARC, and CCL22/MDC receptor, the latter of which are responsible for an increase in the proliferation of cancer cells." (PMID 32781743, 2020). "In mouse embryonic stem cells and progressive cancer cell lines, the CCR4–NOT complex is localized in the nucleus and binds to the promoter region of self-renewal genes." (PMID 32238456, 2020). "CD4+ cell expression of the Th1 marker CXCR3 was increased in cancer septic mice, while expression of the Th2 marker CCR4 was not different between previously healthy septic mice and cancer septic mice." (PMID 27018973, 2016). "Moreover, genes like CCR4 and GSK3A highlighted in this study are already candidate targets for therapy in other cancers." (PMID 21884569, 2011). "Although we demonstrate that antiproliferative activity of RNF219 is at least partially mediated by regulation of CNOT6L expression, further investigation would be required to conclude that the impact of RNF219 activity on cancer progression is mediated by the CCR4‐NOT complex." (PMID 40598799, 2025).
cancer (continued). "However, we did not observe a ZEB1-dependent effect on proliferation of CD8 + T cells in vitro when co-cultured with BMDMs, but a ZEB1-dependent modulation of CD8 + T cell migration by CCL2 and CCL22 as well as CCR2 and CCR4 expression in CD8 + T cell subsets in murine and human cancers." (PMID 40595293, 2025). "Due to the critical role of Tregs in prevention of auto-immune-related diseases, approaches that specifically deplete intratumoral Tregs or that only partially deplete Tregs, by targeting for example CCR8, OX-40, CCR4 and CD2513,33,35,37,73, may be more feasible for use in cancer patients." (PMID 37089449, 2023). "Although the exact mechanism of the altered proportions of CCR4+/CD3+ and central memory CD4+ cells in the gastric mucosa of patients with cancer is unknown, focusing on lymphocytes in the gastric mucosa might help improve our understanding of carcinogenesis after H. pylori eradication." (PMID 36569708, 2022). "In addition to CCR5, CCR4 is a well-known chemokine receptor expressed in Tregs; however, Treg depletion by anti-CCR4 antibody has not translated into therapeutic efficiency against cancer." (PMID 31156643, 2019). "In a phase Ia study in patients with CCR4-negative advanced or recurrent solid cancers, mogamulizumab was tested for its ability to deplete effector Treg cells and thereby strengthen the anti-cancer immune response." (PMID 28361224, 2017). "Moreover, CCR4 could be induced by the cytokine TNF-α in NF-κB-dependent manner and might be involved in TNF-α-induced cancer cells invasiveness." (PMID 27356745, 2016). "In addition, we did not detect a difference in expression of the Th2 marker CCR4 but did observe decreased production of the Th2 effector IL-4 from CD4+ cells taken from cancer septic mice." (PMID 27018973, 2016). "Furthermore, our findings suggest that CCR4 acts downstream of TNF-α and might play a role in TNF-α-mediated cancer cells metastasis." (PMID 27356745, 2016). "However, further studies would be required to confirm whether the impact of RNF219 activity on cancer progression is mediated by the CCR4‐NOT complex." (PMID 40598799, 2025). "While the CCR4-NOT complex has been extensively studied, recent research has highlighted its emerging role in cancer pathophysiology." (PMID 40864769, 2025). "Targeting CCR4 was also effective in disrupting CCL2-induced growth and metastasis without promoting cancer relapse." (PMID 36555280, 2022). "Interestingly, we assessed the mRNA levels of the chemokine receptors CCR4 and CXCR4 in GC cells and found that knockdown or overexpression of CPNE8 significantly regulated their expression, implying that CPNE8 may affect the function of CAFs via modulation of chemokine binding to cancer cells." (PMID 35982908, 2022). "CCR4-NOT transcription complex subunit 2 (CNOT2), a subunit of the CCR4-NOT complex, has been described in cancer progression." (PMID 34680125, 2021). "At the same time, IHC staining in transplanted tumors indicated that the CCR4 antagonist could effectively downregulate the phosphorylation of Vav2 and MLC in cancer cells, but not in tumors treated with CCL2 neutralizing antibody." (PMID 35177591, 2022). "Furthermore, CNOT2, a subunit of the CCR4-NOT complex, is known to be related to angiogenesis, metastasis, cell proliferation, and autophagy in many types of cancer cells." (PMID 36569330, 2022). "We identified that targeting CCR4 could effectively interrupt the activation of HNSCC invasion and metastasis induced by CCL2 without the promoting cancer relapse observed during the subsequent withdrawal period." (PMID 35177591, 2022). "We found that the proportion of CCR4+/CD3+ cells was higher, while the fraction of CD45RA−CD62L+/CD3+CD4+ cells was lower in the lesser curvature of the gastric body of patients with early GC than in those without cancer." (PMID 36569708, 2022).
cancer (continued). "CNOT2 is a subunit of the CCR4-NOT complex that controls mRNA metabolism and the stability of eukaryotic cells and has been reported to play a role in autophagy, apoptosis, proliferation, and angiogenesis in various cancer cells, including those of the colon, lung, and breast." (PMID 36233202, 2022).
infection (54 papers, 2010 to 2025). The state of being infected such as from the introduction of a foreign agent such as serum, vaccine, antigenic substance or organism. "Because CCR4 deficiency increases susceptibility in the chronic phase of infection, we next assessed the gene expression of CCR4 and its ligands CCL17 and CCL22." (PMID 30584243, 2018). "Paradoxically, Ccr4 has been shown to play a detrimental role in bacterial infection as CCR4−/− mice were resistant against lipopolysaccharide-induced lethality, infection by pathogenic E.coli and septic peritonitis induced by cecal ligation and puncture." (PMID 24992587, 2014). "Additionally, we discovered a novel subpopulation of CD14+ monocytes associating with the acute phase of infection that expressed high levels of CCR4, CXCR3, and CCR6, among other markers." (PMID 30150281, 2018). "The Ccr4 gene encodes a cytokine that attracts leucocytes to sites of infection." (PMID 28123054, 2017). "However, there was no major difference in the systemic inflammatory response associated with infection; 3) CCR4 also contributed to the pathogenesis of experimental dengue infection and was relevant for virus-induced liver damage and associated systemic inflammation." (PMID 21206747, 2010). "We did detect a decrease in CCR4+CD4+ memory T cells at week 21 after infection in both the HTLV-1WT- and HTL-1p12KO-infected animals even after the re-depletion of NK cells, CD8+ cells, and monocytes." (PMID 38668247, 2024). "As a monoclonal antibody targeting CCR4, mogamulizumab partially impairs the functions of these immune cells, thereby affecting normal anti‐infection responses in the body." (PMID 39659050, 2024). "Caf1 nuclease CNOT7 protein increased in abundance during infections with AD169 or TB40/E strains of HCMV and expression of mRNAs encoding CCR4 nucleases CNOT6 and CNOT6L were also consistently upregulated 2–3‐fold." (PMID 37846490, 2023). "Based on infection models, the majority of CCR4+ lymphocytes are in an activated state and appear to exert suppressive functions by secreting a number of immunosuppressive cytokines." (PMID 34796183, 2021). "Our results suggest a positive role of CCR4 in cytorhabdovirus infection cycles and explain how the P protein binds to N0 to prevent binding of cellular mRNAs." (PMID 32207684, 2020). "We found that the expression of Ccr4 increased two-fold on day 3 and five-fold on day 7 post-infection." (PMID 31611578, 2019). "Although CCL17 is strongly expressed only at 7 days post-infection and we cannot exclude the possibility that other mediators cooperate in DC migration, the data suggest the involvement of CCR4 in the recruitment of these cells." (PMID 31611578, 2019). "At 30 days of infection, the magnitude and pattern of inflammation was similar between infected WT and CCR4−/− mice, although the magnitude was higher than that observed in the lungs of mice at 15 days of infection." (PMID 30584243, 2018). "To address the contribution of CCR4 during M. tuberculosis infection, we first recovered the bacilli from the lungs of infected WT and CCR4−/− mice at 15 (early), 30 (initial) and 70 (chronic) days of infection." (PMID 30584243, 2018). "According to these findings, it would be interesting to study CD27 and/or CCR4 in samples from active TB patients coming from the site of infection in order to understand better the mechanisms and pathogenesis of the disease." (PMID 30687314, 2018). "At 15 days of infection, lung sections from infected WT and CCR4−/− mice were characterized by focal distribution of predominantly lymphocytes, scattered across bronchioles and vessels." (PMID 30584243, 2018). "Similar to CXCR3, CCR4 is important for the migration of T cells to sites of inflammation or infection." (PMID 29760706, 2018).
infection (continued). "Considering the increase in the magnitude of lung inflammation in the chronic phase of infection in CCR4−/− mice and the role of CCR4 in the recruitment of regulatory T cells into the lungs, we next quantified these cells." (PMID 30584243, 2018). "Sorted spleen Foxp3-GFP+ cells (5 × 105) from non-infected mice were transferred intratracheally into WT or CCR4−/− mice at 60 days of infection." (PMID 30584243, 2018). "The frequency of CD4+ cells was similar between infected CCR4−/− and WT groups at 15, 30 and 70 days of infection." (PMID 30584243, 2018). "Our results above show that the susceptibility to infection, the magnitude of inflammation and the number of CD4+Foxp3+ cells in the lungs are dependent on CCR4." (PMID 30584243, 2018). "Multivariate logistic regression showed a correlation of infection with a cluster containing %CD38+ Ki67− of CXCR5− CXCR3− CCR4+ TEM cells as the only positive coefficient with CD38 expression thus determining the significance." (PMID 27064238, 2016). "In RV infected Tbet deficient mice we observed an increase in airway levels of the chemokine CCL17, a ligand for CCR4 which is expressed on Th2 cells, on day 7 post-infection." (PMID 27683080, 2016). "The induced MDC seems to attract normal CCR4+ T-cells, resulting in the preferential infection of these cells via cell-to-cell contact, and maintain a high frequency of functional CCR4+FoxP3+ Tregs." (PMID 26289727, 2015). "Initially, these results seemed contradictory because we expected a reduced number of Tregs in the secondary local infection in the CCR4-/- mice due to the importance of CCR4, among other receptors, for Tregs migration." (PMID 26197455, 2015). "HCMV requires CCR4‐NOT activity for productive infection, though its own mRNAs are less susceptible to CCR4‐NOT degradation." (PMID 37846490, 2023). "Infection led to robust induction of chemokine and interleukin genes, including Il1b, Il6, Ccl2, Ccl3, Ccl4, Ccl7, Cxcl1, Cxcl2, Cxcl5, Cxcl9, and Cxcl10, and related receptor genes, including Ccr1, Ccr4, Ccr5, Ccr5, Ccr7, Cxcr2, Cxcr5, Il1r2, and Il1rn." (PMID 35487885, 2022). "However, concomitant treatment with the CCR4 antagonist SP50 significantly reduced fungal burden and conferred full protection against infection, thus confirming the vaccine adjuvant properties of CCR4 antagonists." (PMID 33669094, 2021). "However, a great proportion of CD4+ T-cells in MLN remained as single CCR4+ after 30 days (32.68 ± 1.11%) and 60 days of infection (33.44 ± 13.63%)." (PMID 34685494, 2021). "Rhabdoviruses transcribe capped and polyadenylated mRNAs that are potentially targeted by host CCR4, which may be involved in defense against infection." (PMID 32207684, 2020). "Thus, our data point to CCR4 as important molecule involved in the recruitment of cells responsible for the resolution of infection." (PMID 31611578, 2019). "In addition, the migration of these two populations of DCs expressing CCR4 was intensively increased 3 and 7 days post-infection." (PMID 31611578, 2019). "In addition, the number of Foxp3+ cells expressing CCR4+ was also increased at day 7 post infection." (PMID 31611578, 2019). "In addition, the expression of IFN-β and IL-12p40 presented a profound reduction in CCR4−/− mice after 7 days of infection." (PMID 31611578, 2019). "Interestingly, we also found a small subpopulation of CD14+ monocytes with distinctly higher expression of previously unreported markers (CCR4, CXCR3, and CCR6) that also associated with the acute phase of infection." (PMID 30150281, 2018). "However, a significant increase in the number of CD4+ cells was found in the lungs of infected CCR4−/− animals at 15 and 70 days of infection." (PMID 30584243, 2018). "Since Tregs and IL-10 may contribute to persistence of an infection with H. suis, we hypothesized that CCR4 antagonists might help to induce protective immunity." (PMID 26115373, 2015).
infection (continued). "Because CCR4-/- mice were more resistant against septic insult, we hypothesized that these animals may also exhibit a higher resistance to a secondary infection challenge." (PMID 26197455, 2015). "However, infection induced the expression of CCR4 and CCR5 in these cells." (PMID 34685494, 2021). "In addition, CCR4 antagonists may be used to increase the protective immune response to vaccination with fungal antigens and to confer protection against subsequent infection." (PMID 33669094, 2021). "Thus, CCR4−/− mice are more resistant than their WT counterparts at 15 days post infection." (PMID 30584243, 2018). "Furthermore, infection of regulatory CD4+CD25+CCR4+ T cells might also determine the outcome of different immune responses in HTLV-I infection." (PMID 24470869, 2013). "When looking at the effects of infection on expression of immune-related genes in the proximal colon we found an upregulation of genes related to type-2 responses such as CCL26, CCR4, and RETNLB (fold changes 1.4, 1.5 and 1.4, respectively)." (PMID 38081984, 2023). "Based on previous results, we resorted to a murine model of CF challenged with A. fumigatus and first evaluated the expression of CCR4 and its ligands CCL17 and CCL22 during infection." (PMID 33669094, 2021). "In the present study, we have assessed the potential therapeutic efficacy of a CCR4 small molecule antagonist, SP50, discovered via an in silico-based approach, against a variety of pre-clinical settings of infection with the fungus Aspergillus fumigatus." (PMID 33669094, 2021). "After 30 days of infection, CXCR3+CCR5+CCR4+ CD8+ T-cells were predominant in the blood (Student’s t-test, p = 0.001), as reported for CD4+ T-cells." (PMID 34685494, 2021). "We found that relatively few MAIT cells expressed CCR2, CCR4, CCR6, CXCR3, CXCR4, and CCR9 in the lungs, spleen, thymus, and LP both before and after infection." (PMID 32849637, 2020). "To verify that CCR4 expression is induced in Treg throughout CVB5 infection, we analyzed Foxp3+ cells in the PLNs on days 0, 7 and 14 post-infection." (PMID 31611578, 2019). "CCR4−/− mice exhibited a lower frequency of CD4+Foxp3+ cells at 15, 30, and 70 days of infection than their wild-type counterparts." (PMID 30584243, 2018). "CCR4−/− mice exhibited a lower frequency of CD4+Foxp3+ cells in the early (15 days), initial (30 days), and chronic (70 days) phases of infection than their respective WT counterparts." (PMID 30584243, 2018). "At the earliest hours after infection, DGK activity ensured recruitment of naïve CD8 T cells to the dLNs via upregulating CCR4, CCR5, and CXCR3." (PMID 27014906, 2016). "Notably, CTLA-4 expression was also increased in CD4+ CCR4+ CXCR3− TH2 and CD4+ CCCR6+ CCR4− CXCR3− TH9 at 8-weeks and 12-weeks post-infection, respectively." (PMID 39411786, 2024). "An open possibility is differential activity of the CCR4‐NOT deadenylation complex toward HCMV mRNAs during infection." (PMID 37846490, 2023). "In both sets of CCR4-tropic infection, the difference was not large, and even in the opposite direction for the Experiment #1 dataset." (PMID 38156317, 2023). "Naturally, the proportion of CD4+CCR4+ lymphocytes in placebo-treated cats was slightly higher than in uninfected control cats, since FIV-infected cats will mount some Th2 anti-inflammatory response to infection." (PMID 37112803, 2023). "HCMV protein UL38 is responsible for the translational upregulation of many cellular proteins during infection through activation of mTORC1, and it will be interesting to explore if this mechanism also controls CCR4‐NOT." (PMID 37846490, 2023). "Interestingly, expression of skin-homing receptors CCR4 and CCR10 was up-regulated in CD4+ cells from the mesLNs and in the circulation of worm-infected mice 2 and 3 weeks after infection." (PMID 34931000, 2022).